AURKA (aurora kinase A)
Diseases named in the same sentence as AURKA in open-access papers (continued):
Sharing a sentence is not in itself a finding about the gene and the disease.
ovarian carcinoma (continued). "In the current study, we investigated the relatively undefined role of AURKA in mediating the DDR and DNA repair in ovarian carcinoma cells and discovered that AURKA regulates the activity of PARP and DNA-PKcs, a key signaling molecule in the error-prone NHEJ pathway." (PMID 28881569, 2017). "AURKA is thought to play an important role in ovarian tumor biology, because activation of this kinase either by genomic amplification or increased expression is a common feature of ovarian carcinoma cell lines and primary tumors." (PMID 28881569, 2017). "Furthermore, consistent with a report in ovarian cancer cells, AURKA function was critical to the migration of the tested melanoma cell lines, including the MITFAmp UACC-62 and UACC-257 cells." (PMID 26962685, 2016). "For example, AURKA was found overexpressed in the early stage ovarian tumors, therefore suggesting that the alteration of AURKA could be an early event of ovarian cancer." (PMID 26317392, 2015). "Furthermore, overexpressed AURKA decreases BRCA2 expression in ovarian cancer." (PMID 39334449, 2024). "Particularly, ovarian cancer-associated cell cycle activators, namely cyclin A2 (CCNA2) and aurora kinase A (AURKA), were downregulated by E47, thereby revealing the conserved effects of E47 in ovarian cancer cells." (PMID 35740568, 2022). "The synthetic lethality of ARID1A and AURKA was verified in three different ARID1A isogenic CRC pairs and three ovarian cancer cell lines with different ARID1A statuses; however, the synthetic lethality in ovarian cancer cells needs to be further investigated." (PMID 30097580, 2018). "Inhibitors against proteins coded by these genes, such as AURKA and B or CHEK1, are currently in clinical development, so our findings provide support for the specific development of those agents in ovarian cancer." (PMID 29575713, 2018). "Taken together, these data suggest that AURKA inhibition induced DNA DSBs and elevated error-prone NHEJ repair of DNA DSBs with incompatible ends in both PARPi-sensitive and -resistant ovarian carcinoma cells." (PMID 28881569, 2017). "Taken together, these observations suggest that AURKA regulates PARP activity in PARPi-sensitive and -resistant ovarian carcinoma cells." (PMID 28881569, 2017). "Pharmacological inhibition of Aurora kinase A (AURKA), a key cell cycle regulator critical for mitotic events, has been recently shown to suppress, at least partially, EMT in pancreatic as well as ovarian cancer cell lines." (PMID 27379175, 2016). "There is an overexpression of both AURKA and TPX2 in many different cancer forms, including ovarian cancer, and it has been proposed that TPX2 and AURKA is a functional unit with oncogenic properties." (PMID 23029477, 2012). "Thus, the AURKA/SOX8/FOXK1 signaling axis promotes chemoresistance by suppressing cell senescence and inducing glucose metabolism in ovarian cancer." (PMID 39334449, 2024). "lncRNA TUG1 also regulated aurora kinase A (AURKA), or sponged miR-1299 by up-regulating notch receptor 3(NOTCH3) to promote the proliferation and invasion of epithelial ovarian cancer cells." (PMID 34039257, 2021). "To further confirm the roles of AURKA and EZH2 in the cell cycle pathway of cancer stem cells, we analyzed single-cell RNA-seq datasets of ovarian carcinoma in the CancerSCEM database (Cancer Single-cell Expression Map database) based on the E-MTAB-8559 dataset." (PMID 35059393, 2021). "column 6) paths containing three known ovarian cancer oncogenes CCNE1, AURKA and RAB2534–36." (PMID 30944378, 2019).
ovarian carcinoma (continued). "The current study tests the hypothesis that AURKA regulates the DDR and DNA repair pathways in ovarian carcinoma cells." (PMID 28881569, 2017). "Recent studies have shown that inhibition of AURKA can sensitize cancer cells to CDDP in gastric cancer and its overexpression may predict platinum resistance in epithelial ovarian cancer." (PMID 28417568, 2017). "Amplification of 20q13 may be particularly heterogeneous as AURKA, TGIF2, PTPN1 and ZNF217, and ADRM1, and other genes, have been cited as drivers of 20q13 amplification in ovarian cancer." (PMID 19419571, 2009). "Collectively, these results reveal new non-mitotic functions for AURKA in the regulation of DNA repair, which may inform of new therapeutic targets and strategies for treating ovarian cancer." (PMID 28881569, 2017). "Inhibition of AURKA could reduce the activity of poly (ADP-ribose) 1 level and promote non-homologous end joining repair (NHEJ) mechanisms in ovarian carcinoma cells." (PMID 34336648, 2021).
prostate carcinoma (64 papers, 2007 to 2026). A carcinoma that arises from epithelial cells of the prostate gland. "In this study, we confirmed that AURKA overexpression is associated with an invasive tumor phenotype and poor prognosis in prostate cancer, consistent with pan-cancer." (PMID 40718709, 2025). "AURKA expression in combination with other indicators helps to stratify recurrence risk in patients with prostate cancer." (PMID 40718709, 2025). "On the other hand, knockdown of ARPC1B in prostate cancer cells has been observed to reduce the proliferation, migration, and invasion and cause cell cycle arrest at the G2/M phase via the downregulation of AURKA." (PMID 37304283, 2023). "Overexpression of the centrosome-associated serine/threonine kinase Aurora Kinase A (AURKA) has been demonstrated in advanced prostate cancer and high-grade prostatic intraepithelial neoplasia lesions." (PMID 36006421, 2022). "We observed that the knockdown of WDR62 results in loss of TPX2 and AURKA protein suggesting WDR62 regulates the stability of this protein complex in prostate cancer cells." (PMID 34326322, 2021). "We also studied the expression of AURKA in clinical prostate cancer samples and its association with the AR expression levels." (PMID 29269934, 2017). "Nevertheless, the AurkA polymorphism has been observed in many tumour types, e.g., oesophageal, breast, hepatocellular, and prostate cancer." (PMID 24980817, 2014). "Thus, we aimed to investigate whether depletion of SNHG4, RRM2, EZH2, AURKA or TK1 can cause prostate cancer cell senescence and affect cell viability." (PMID 37596700, 2023). "In this study, we revealed the heterogeneity of AURKA expression in epithelial cells and the potential benefits of combination therapy for prostate cancer." (PMID 40718709, 2025). "In summary, our study highlighted the various oncogenic roles of AURKA in prostate cancer, and the heterogeneity of its expression has different molecular characteristics and clinical prognosis." (PMID 40718709, 2025). "Taken together, the results obtained from cell models are consistent with our conclusion of the tumor-promoting role of AURKA in prostate cancer development." (PMID 40718709, 2025). "In prostate cancer, Aurora kinase-A (AURKA) collaborates with YBX1 to promote aggressive carcinogenic phenotypes and chemoresistance." (PMID 40799245, 2025). "AURKA inhibitors have limited efficacy as monotherapy in prostate cancer, consistent with observations in other solid tumors." (PMID 40718709, 2025). "Other prostate cancer-associated somatic mutations were consistent in some PDOs and parental tumours, such as BRCA1, ALK, STED2, TET2, TRPM8, AURKA, ERBB2, GATA2." (PMID 41403018, 2025). "Several early studies found that Aurora kinase A is overexpressed at the transcript and protein levels in various malignancies, including leukemia, prostate cancer, esophageal adenocarcinoma, and pancreatic cancer cell lines." (PMID 40723362, 2025). "The accurate population stratification of AURKA subgroups in prostate cancer can facilitate personalized treatment." (PMID 40718709, 2025). "We also investigated the role of AURKA in prostate cancer (DU145) and pancreatic cancer (PaTu8988t) cells." (PMID 37965456, 2023). "AR inhibition enhanced the expression of NK1R, which mediated the PKCα-AURKA/N-Myc pathway in prostate cancer cells." (PMID 37385990, 2023). "In prostate cancer, AURKA is reported to contribute to the epithelial–mesenchymal transition and neuroendocrine differentiation." (PMID 34593983, 2023). "Conducting experiments in EAC, prostate cancer, and pancreatic cancer cells, revealing that inhibiting AURKA expression substantially reduced cell viability." (PMID 37965456, 2023).
prostate carcinoma (continued). "Treating these cells with AURKA-GapmeR or Aur-I resulted in decreased AURKA mRNA expression and reduced cell viability in both prostate cancer and pancreatic cancer cells." (PMID 37965456, 2023). "During antiandrogen treatment, the enhanced NK1R expression activates PKC/AURKA/N-Myc pathway in prostate cancer cells, mediating the induction of NE markers and NE-related gene expression and promoting tumor growth." (PMID 37385990, 2023). "The results suggested that high expression of SNHG4 was correlated with RRM2/EZH2/AURKA/TK1 overexpression in prostate cancer tissue specimens." (PMID 37596700, 2023). "Meanwhile, the IDOAMP downregulated the expression of human Aurora kinase A that was overexpressed in prostate cancer." (PMID 35965682, 2022). "AURKA overexpression is vital for prostate cancer tumorigenesis and can function to allow tumor cells to evade therapy." (PMID 35317831, 2022). "AURKA has also been shown to promote survival of prostate cancer cells by suppressing autophagy and furthermore the autophagy-induced apoptosis through inhibition of Akt phosphorylation." (PMID 33572108, 2021). "Another AURKA inhibitor, MLN8054, sensitizes androgen-insensitive prostate cancer to radiation; this sensitization is associated with sustained DNA double-strand breaks." (PMID 33451333, 2021). "As some studies have shown that the expression level of the AURKA gene increased in many cancer cells including stomach, liver, colorectal, ovarian, breast, lung, bladder, head and neck, and prostate cancers." (PMID 34337875, 2021). "On the other hand, it has been widely reported that AURKA is an oncogene to promote tumorigenesis in multiple types of cancer including solid tumors (such as bladder cancer, prostate cancer, colon cancer) and hematological malignancies." (PMID 34384030, 2021). "This experiment demonstrated that WDR62 interacts with TPX2 and AURKA likely forming a protein complex in prostate cancer cells." (PMID 34326322, 2021). "In contrast, AURKA transcripts were upregulated in only 15.4% of prostate cancer (PCa) and 76.3% of BPH specimens, indicating that post-translational stabilization of AURKA is a critical factor in promoting its deregulation." (PMID 34625072, 2021). "In prostate cancer AURKA has been shown to block the degradation of the transcription factor N-Myc, and the cooperative function of these two drives the progression prostate cancer." (PMID 33572108, 2021). "Mechanistically, our data demonstrated that WDR62 modulates the activity of AURKA by stabilizing the AURKA/TPX2 protein complex in prostate cancer cells." (PMID 34326322, 2021). "AURKA-mediated phosphorylation of CHIP at Ser273 promotes androgen degradation in castration-resistant prostate cancer." (PMID 33451333, 2021). "It has been shown that AURKA is important for development of prostate cancer, and that it represents a possible target for treatment." (PMID 32252623, 2020). "Overexpression of AURKA is reported in numerous tumors including melanoma, leukemia, pancreatic, ovarian, gastrointestinal, esophageal kidney, colon, breast and prostate cancer (PCa)." (PMID 33158056, 2020). "The study of a large set of treatment-related NEPCs showed AURKA amplification in 65% of primary prostate cancers and 86% of metastases and concurrent MYCN amplification was detected in 69% of treated prostate cancers and 83% of metastases." (PMID 31366128, 2019). "In local recurrent CRPC specimens and CRPC metastases, the frequency of AURKA positivity was significantly higher compared to hormone naïve prostate cancer samples (P < 0.0001 and P < 0.0001, respectively)." (PMID 29269934, 2017). "We also report a transcriptional level correlation of AURKA and AR in clinical AR-positive prostate cancer specimens in two independent prostate cancer cohorts." (PMID 29269934, 2017). "At a similar rate as that seen in local CRPC specimens, AURKA-positive metastases were found in 52% of the men who died of prostate cancer." (PMID 29269934, 2017).
prostate carcinoma (continued). "We have previously found that AURKA is upregulated in prostate cancer cells that overexpress AR (VCaP and LNCaP cells stable-transfected with AR) under DHT stimulation and is overexpressed in CRPC18,19." (PMID 29269934, 2017). "Together, these findings suggest that the expression of AURKA is regulated by androgen in prostate cancer cells that highly express AR, emphasizing its potential as a therapeutic target in patients with CRPC." (PMID 29269934, 2017). "Our previous analyses suggested that Aurora kinase A (AURKA) is regulated by androgens in prostate cancer cells that express high levels of AR." (PMID 29269934, 2017). "Consequently, further exploration of the role of AURKA in prostate cancer is required to guide precision therapy with AURKA inhibitors." (PMID 40718709, 2025). "Conversely, certain experiments indicate that NEPC undergoes transdifferentiation from prostatic adenocarcinoma, supported by the detection of prostate cancer-specific mutations (for example, ERG rearrangements) and gene amplifications (for example, AURKA and MYCN) in both subtypes." (PMID 38534956, 2024). "Therefore, decreasing AURKA expression can induce autophagy and suppress proliferation of prostate cancer cells." (PMID 35317831, 2022). "Indeed, AR-negative prostate cancer cells have been shown to respond to AURKA, FGFR, or MAPK inhibitors, in line with the notion that these pathways are activated as a result of the lineage switch." (PMID 33420371, 2021). "hsa-mir-25 is related to the invasion of prostate cancer and may be a signaling mechanism of aurora kinase A or integrin." (PMID 34512870, 2021). "Notably, formation of primary cilia is suppressed in several cancers in which expression of AURKA is increased, including epithelial ovarian cancer, prostate cancer, pancreatic ductal adenocarcinoma, and glioblastoma." (PMID 34944109, 2021). "MYCN is amplified in some forms of neuroblastoma and prostate cancers and predicts poor prognosis; therefore, inhibition of AURKA–MYCN binding might also be a useful therapeutic approach in these cancers." (PMID 34944109, 2021). "We hypothesized that WDR62 may regulate the stability or function of the TPX2/AURKA protein complex in prostate cancer cells." (PMID 34326322, 2021). "Aurora A (AURKA) is overexpressed in all stages of prostate cancer including CRPC." (PMID 33158056, 2020). "Moreover, the enhancement of miR-199a methylation results in the down-regulation of miR-199a-3p, and miR-199a-3p inhibits aurora kinase A and attenuates xenograft tumor growth in prostate cancer." (PMID 33365310, 2020). "Furthermore, there is some evidence that indicates the interaction between AURKA and AR in prostate cancer 14-16." (PMID 31871591, 2019). "We found that AURKA expression correlates with the AR level in hormone-naïve prostate cancer specimens, suggesting the AURKA expression may play a role in the early progression of prostate cancer." (PMID 29269934, 2017). "AURKA was found to be overexpressed in prostate cancer, especially in CRPC specimens." (PMID 29269934, 2017). "Different AURKA levels seen in different prostate cancer metastases may indicate variability in androgen sensitivity in the different metastases." (PMID 29269934, 2017). "Furthermore, MYCN and Aurora Kinase A (AURKA) have higher expression in late stage neuroendocrine prostate cancer than other prostate cancer types and they have been suggested to cooperate in inducing differentiation." (PMID 28358317, 2017). "Hence, further analysis of the mechanisms and roles of AURKA in different subsets may help us in precision therapy with AURKA inhibitors, especially in urological tumors such as prostate cancer." (PMID 40718709, 2025). "However, prostate cancer exhibits a unique dependence on AR and tumor stemness, which may enhance the role of AURKA in promoting genomic instability and maintaining tumor invasiveness after AR deprivation." (PMID 40718709, 2025).